ANGPTL2 (angiopoietin like 2)
Diseases named in the same sentence as ANGPTL2 in open-access papers (continued):
Sharing a sentence is not in itself a finding about the gene and the disease.
breast carcinoma (15 papers, 2015 to 2023). "Taken together with these findings, ANGPTL2 likely plays both direct and indirect roles in tumor angiogenesis in the case of breast cancers, and these effects may underlie enhanced bone metastasis." (PMID 25773070, 2015). "In breast cancer cells, angiopoietin-like protein 2 (ANGPTL2) was found to upregulate CXCR4 and promote bone metastasis in an intracardiac bone metastasis mouse model." (PMID 37025604, 2023). "Given the secreted glycoprotein role of ANGPTL2 protein, Motoyoshi and colleagues uncovered that the serum ANGPTL2 levels are significantly upregulated in breast cancer patients with metastasis and are potential predictors of metastatic breast cancer." (PMID 37691929, 2023). "With the exception of angiopoietin-like-2 and DPPIV in the BRCA-mutated breast cancer lines, the other differences in ADSC-induced proteins are of minor quantitative nature." (PMID 34228231, 2021). "Both in vitro and in vivo experiments showed that the levels of angiopoietin-like 2 secreted from breast cancer cells increased with cell proliferation and cancer progression." (PMID 34228231, 2021). "In pre-clinical models, it has been demonstrated that ANGPTL2 strengthens responsiveness of breast cancer cells to chemokine (C-X-C motif) ligand 12 (CXCL12) by the up-regulation of chemokine (C-X-C motif) chemokine receptor 4 (CXCR4) in those cells." (PMID 29389861, 2018). "There are some evidences about how ANGPTL2 promotes breast cancer cells’ recruitment to bone metastatic sites." (PMID 29389861, 2018). "In this study, we showed that ANGPTL2 significantly up-regulated CXCR4 expression in breast cancer cells, which likely enhances their responsiveness to CXCL12." (PMID 25773070, 2015). "Here, we show that tumor cell-derived angiopoietin-like protein 2 (ANGPTL2) increases responsiveness of breast cancer cells to CXCL12 by promoting up-regulation of CXCR4 in those cells." (PMID 25773070, 2015). "We also demonstrated that suppression of breast cancer cell-derived ANGPTL2 attenuated breast cancer metastasis to lung tissue in vivo using xenograft models created by implanting MDA-MB231 breast cancer cells into the mouse mammary fat pad26." (PMID 25773070, 2015). "Finally, ANGPTL2 expression was positively correlated with CXCR4 expression levels in primary tumor tissue from breast cancer patients." (PMID 25773070, 2015). "ANGPTL2 expression at the primary tumor site was also significantly correlated with tumor size (T-factor), positivity for lymph node metastasis, and severity of breast cancer stage (P < 0.001)." (PMID 25773070, 2015). "Furthermore, our findings suggest that in bone tissue, CXCL12-activated CXCR4 signaling in breast cancer cells induced by ANGPTL2 also accelerates osteolysis and bone engraftment." (PMID 25773070, 2015). "In summary, here we show that breast cancer cell-derived ANGPTL2 may play important roles in bone metastasis by enhancing responsiveness of breast cancer cells to bone tissue-secreted CXCL12 through up-regulated tumor cell CXCR4 expression." (PMID 25773070, 2015). "To investigate whether ANGPTL2 increases CXCR4 expression in other breast cancer cells, we generated T47-D lines that constitutively express ANGPTL2 (T47-D/ANGPTL2) and control vector-only lines (T47-D/Control)." (PMID 25773070, 2015). "Overall, these findings suggest that ANGPTL2 may promote breast cancer progression, possibly by activating CXCR4 and MMP-13." (PMID 25773070, 2015). "Here we demonstrate that breast cancer cell-derived ANGPTL2 may play an important role in metastasis of breast cancer cells to bone." (PMID 25773070, 2015). "Moreover, circulating ANGPTL2 levels match the clinical features of breast cancer progression, raising a possibility that serum ANGPTL2 levels in breast cancer patients could be a potential marker of metastasizing ability." (PMID 29389861, 2018).
breast carcinoma (continued). "In addition, we used a xenograft mouse model established by intracardiac injection of tumor cells to show that ANGPTL2 knockdown in breast cancer cells attenuates tumor cell responsiveness to CXCL12 by decreasing CXCR4 expression in those cells, thereby decreasing bone metastasis." (PMID 25773070, 2015). "Both ANGPTL2 and CXCR4 expression levels were positively correlated with high MMP-13 expression in breast cancer patient specimens." (PMID 25773070, 2015). "Next, we analyzed a potential relationship between ANGPTL2 and CXCR4 expression in primary tumors from 181 breast cancer patients." (PMID 25773070, 2015). "Angiopoietin-like 2 is prominently overexpressed in MDA-MB-436 in response to F13-ADSC-supernatant compared to MDA-MB-231 wildtype cells and the same effect is detectable in HCC1937 breast cancer cells." (PMID 34228231, 2021). "In addition, tumor cell-derived angiopoietin-like protein 2 (Angptl2) induces CXCR4 and activates CXCL12/CXCR4 signaling in breast cancer cells, leading to bone metastasis." (PMID 33096815, 2020). "Finally, we found that ANGPTL2 and CXCR4 expression levels within primary tumor tissues from breast cancer patients are positively correlated." (PMID 25773070, 2015). "Finally, we observed a positive correlation of ANGPTL2 and CXCR4 expression in primary tumor tissues from breast cancer patients." (PMID 25773070, 2015). "Additionally, migration of breast cancer cells in response to CM of ADSCs proved to be equivalent or slower for BRCA1/2 mutated versus nonmutated cancer cells and, with exception of angiopoietin-like 2, induced expression of adipokines showed no major difference." (PMID 34228231, 2021).
colorectal cancer (15 papers, 2017 to 2026). A primary or metastatic malignant neoplasm that affects the colon or rectum. "To localize ANGPTL2 protein expression in colon, we performed IHC for ANGPTL2 protein in mice and in human normal colon tissue associated with colorectal cancer (Fig EV3A)." (PMID 28043948, 2017). "Moreover, The R399H ANGPTL2 mutation frequently occurs in endometrial cancer, while the G402S ANGPTL2 mutation often appears in colorectal cancer." (PMID 37751067, 2024). "ANGPTL2 is a reported prognostic and diagnostic marker of GC and colorectal cancer." (PMID 35768842, 2022). "Moreover, circulating ANGPTL2 allowed to distinguish between patients with EC from healthy controls with high diagnostic accuracy (AUC value > 0.9) bracing its diagnostic marker role, as for gastric cancer (GC) and colorectal cancer (CRC)." (PMID 29389861, 2018). "Based on these findings, we herein investigated the role of periodontitis-induced ANGPTL2 in the progression of colorectal cancer (CRC) in mice." (PMID 41899283, 2026). "Increased ANGPTL2 expression in colorectal cancer (CRC) cells improves the β-catenin pathway signaling and boosts tumor cell proliferation." (PMID 36291283, 2022). "ANGPTL2 has been shown to contribute to the proliferation and invasion of gastric cancer cells, and it has been reported to be a potential biomarker for colorectal cancer." (PMID 31534470, 2019). "In intestine, tumor cell‐derived ANGPTL2 renders colorectal cancer cells resistant to chemotherapy via anti‐apoptotic signaling." (PMID 28043948, 2017). "Studies on ANGPTL2 have shown that it can contribute to colorectal cancer cell proliferation, migration, and invasion, promote CRC cell survival after anti-neoplastic drug treatment (by regulating anti-apoptotic BCL-2 family genes), and develop resistance to chemotherapy." (PMID 34445141, 2021). "In addition, ANGPTL2 enhanced the progression and drug resistance in colorectal cancer." (PMID 36917086, 2023). "HOXB9 activation is reported to induce chemoresistance to anti-VEGF bevacizumab in colorectal cancer xenograft mouse models via altering angiogenic factors expression such as CXCL1, TGF-β1, angiopoietin-like 2 (Angptl2), and IL8." (PMID 33666848, 2021). "In addition, it has been proposed that primary tumour might be the source of elevated serum ANGPTL2 measured in colorectal cancer patients, since high levels of ANGPTL2 in tumour tissues and in matched serum samples were both associated with tumour size, distant metastasis, and cancer stage." (PMID 29138671, 2017).
endothelial dysfunction (14 papers, 2013 to 2026). In vascular diseases, endothelial dysfunction is a systemic pathological state of the endothelium (the inner lining of blood vessels) and can be broadly defined as an imbalance between vasodilating and vasoconstricting substances produced by (or acting on) the endothelium. "ANGPTL2 has also been connected to endothelial dysfunction and cardiovascular disorders through modulation of LDL metabolism." (PMID 34422408, 2021). "ANGPTL2 (angiopoietin-like protein 2), endocan, thrombomodulin, and soluble versions of vascular endothelial growth factor 1 and 2 receptors (sVEGFR1/2) are all markers of endothelial dysfunction." (PMID 34768884, 2021). "Angptl2(−/−) mice exhibited less severe endothelial dysfunction compared with wild-type mice when fed a high-fat diet." (PMID 33256685, 2020). "On the other hand, endothelial dysfunction, macrophage infiltration/activation, and perivascular adipose tissue cooperatively contribute to increase ANGPTL2 production, leading to NFκB-dependent chronic inflammation in the vessel wall." (PMID 29138671, 2017). "Excessive activation of ANGPTL2 signaling in these cells could drive endothelial dysfunction, tissue fibrosis, and organ degeneration, hallmarks of inflammaging‐related pathology." (PMID 41508557, 2026). "Our results provide evidence that obese children and adolescents encounter higher circulatory levels of ANGPTL2 and ANGPTL3 compared to normal-weight children, which might be associated with MetS and endothelial dysfunction." (PMID 34422408, 2021).
type 2 diabetes (14 papers, 2013 to 2025). "Because the changes in ANGPTL2 mRNA expression appeared accurately to reflect alterations in ANGPTL2 secretion, the discrepancy between the two measurements in obese patients associated with type 2 diabetes occurred to a surprisingly great extent." (PMID 30228336, 2018). "Higher levels of hemoglobin A1c and high-sensitivity C-reactive protein were significantly associated with elevated serum ANGPTL2 concentration in subjects with type 2 diabetes." (PMID 25889082, 2015). "In that analysis, the risk of developing type 2 diabetes was significantly higher in the highest ANGPTL2 quartile (i.e., ≥ 3.41 ng/ml) than in the lowest quartile (hazard ratio, 1.80)." (PMID 25889082, 2015). "Elevated serum ANGPTL2 levels positively associate with the development of type 2 diabetes in a general Japanese population." (PMID 26132105, 2015). "Further studies are needed to identify the association of human adipose ANGPTL2 expression with the development of type 2 diabetes." (PMID 24733068, 2014). "This review discusses two prospective cohort studies that evaluated the prognostic value of ANGPTL2 in individuals with type 2 diabetes, focusing on the risks of lower-extremity artery disease (LEAD) and peripheral arterial disease (PAD)." (PMID 40278353, 2025). "In conclusion, we found that the serum ANGPTL2 concentration is significantly and positively associated with carotid IMT in human subjects with type 2 diabetes." (PMID 25889082, 2015). "We measured the circulating ANGPTL2 level in 166 subjects (92 men and 74 women; mean age of 60.0 years) with type 2 diabetes." (PMID 25889082, 2015). "In our current study, the serum ANGPTL2 concentration is significantly and positively associated with carotid IMT in subjects with type 2 diabetes (r = 0.220, p < 0.01)." (PMID 25889082, 2015). "These authors demonstrated that serum ANGPTL2 was significantly increased in patients with CHD or type 2 diabetes." (PMID 25889082, 2015). "This concept might be applicable to many other Angptl2-related diseases and might explain why Angptl2-related diseases such as chronic kidney disease and type 2 diabetes target different tissues or organs in different patients." (PMID 26839315, 2016). "Finally, we examined the clinical and biochemical factors that contributed to the elevated serum ANGPTL2 concentrations in our subjects with type 2 diabetes." (PMID 25889082, 2015). "Serum ANGPTL2 was significantly higher in non-diabetic obese patients than normal weight patients; in obese patients, it was significantly higher when type 2 diabetes was also present." (PMID 30228336, 2018). "We compared ANGPTL2 mRNA expression in the two separate fat depots, abdominal SAT and VAT, in obese women (with or without type 2 diabetes) and normal weight women." (PMID 30228336, 2018).
heart failure (11 papers, 2015 to 2026). Inability of the heart to pump blood at an adequate rate to meet tissue metabolic requirements. "Higher circulating ANGPTL2 levels were reported in heart failure patients, and higher levels were associated with increased (~3-fold) risk of heart failure." (PMID 29138671, 2017). "Because several adipocytokines are known to be associated with heart failure (HF), here we investigated the association of ANGPTL2 and HF in Taiwanese subjects." (PMID 26397985, 2015). "Multivariate logistic regression analyses showing the odds ratios (OR) for the presence of heart failure in different levels of circulating ANGPTL2." (PMID 26397985, 2015). "The effects of ANGPTL2 on the heart are, however, less clear: on the one hand, circulating or cardiac ANGPTL2 levels were found to be independent predictors of the presence of heart failure." (PMID 38426206, 2024). "Although most Angptl2-KD mice present mild-to-moderate AVS, ~5% of animals develop a more severe AoV phenotype and are more susceptible to developing cardiac hypertrophy and heart failure." (PMID 36414704, 2022). "In addition, the authors showed that heart-derived ANGPTL2 contributed to accelerate heart failure, by lowering ventricular contractility and by decreasing myocardial energy metabolism." (PMID 29138671, 2017). "Overall, these studies suggest that therapeutic ANGPTL2 suppression could antagonize development of heart failure." (PMID 27677409, 2016). "Given that cardiac senescence is a potential driver of cardiovascular disease, these findings suggest that ANGPTL2‐mediated inflammation and cellular senescence contribute to HFD‐induced heart failure." (PMID 41508557, 2026). "In patients, high circulating ANGPTL2 levels predict the occurrence of CVD and could be a marker of heart failure." (PMID 38426206, 2024). "We also report that adult Angptl2-KD mice do not develop severe LV dysfunction or heart failure." (PMID 36414704, 2022). "Altogether, our data suggest that Angptl2-KD mice is a model of mild-to-moderate congenital AVS that does not translate into severe cardiac dysfunction and heart failure in adults." (PMID 36414704, 2022). "Adult Angptl2-KD mice, from the age of 2 to 10 months, develop AVS characterized by collagen disorganization and elevated trans-aortic gradient, without developing severe LV dysfunction or heart failure." (PMID 36414704, 2022).
gastric cancer (10 papers, 2018 to 2025). A primary or metastatic malignant neoplasm involving the stomach. "On the other hand, ANGPTL2 was overexpressed in gastric cancer tissues and a further upregulation was associated with tumor progression, early recurrence and poor prognosis." (PMID 29389861, 2018). "More interestingly, recent studies have reported high expression of ANGPTL2 in various malignant tumors including; non-small cell lung cancer, colorectal cancer, prostate cancer, and gastric cancer." (PMID 31384179, 2019). "High levels of ANGPTL2 have been found in lung and gastric cancer patients." (PMID 36917086, 2023). "ANGPTL2 contributes to proliferation and invasion of gastric cancer cells." (PMID 34447409, 2021). "Furthermore, ANGPTL2 has been shown to promote the genesis and development of pulmonary cancer cells as well as gastric cancer by accelerating the incidence and progression of disease." (PMID 31384179, 2019). "Likewise EC, the serum levels ANGPTL2 in gastric cancer patients were higher than those of healthy controls." (PMID 29389861, 2018). "Overexpression of ANGPTL2 has been reported in diffuse gastric adenocarcinoma compared with normal gastric tissue, according to Chen26 (FC = 2.239) and DErrico's (FC = 2.360) dataset, while ANGPTL2 was also upregulated in gastric cancer (FC = 2.249) according to Wang's dataset." (PMID 32410376, 2020). "Additionally, a report showed that ANGPTL3 and ANGPTL6 expression was lower in gastric cancer (GC) tissues compared to normal gastric tissues, while ANGPTL1, ANGPTL2, and ANGPTL4 were more highly expressed in GC tissues than in normal gastric tissue." (PMID 39708716, 2025).
glioma (10 papers, 2014 to 2025). A benign or malignant brain and spinal cord tumor that arises from glial cells (astrocytes, oligodendrocytes, ependymal cells). "Additionally, tumorigenesis assays demonstrated that inhibiting ANGPTL2 caused a decrease in glioma tumor growth in vivo." (PMID 37660060, 2023). "ANGPTL2 is a secreted protein that has been demonstrated to facilitate tumor growth and invasion in various cancer types, including glioma." (PMID 37660060, 2023). "Nevertheless, ANGPTL2 knockdown induced a significant decline in the invasive capacity and proliferation of glioma cells." (PMID 37660060, 2023). "The inhibition of multiplication and invasion in glioma cells has been attributed to the decline in ANGPTL2 levels, which effectively suppresses the ERK/MAPK pathway." (PMID 38045808, 2023). "Noteworthy, ANGPTL2 silencing led to a reduction in the protein levels of p-ERK1/2 in glioma cells, consequently impeding the ERK/MAPK signaling pathway’s activity." (PMID 37660060, 2023). "Both glioma tissues and cells have shown significant elevations of ANGPTL2 expression levels." (PMID 37660060, 2023). "The results show that the expression of CDK4 and ANGPTL2 was significantly associated with CNV, indicating that the expression of CDK4 and ANGPTL2 in glioma may be affected by CNV." (PMID 36358948, 2022). "In addition to these well-established glioma markers, we identified several other proteins that have never been associated with glioma biology including (e.g., SLC1A3, CLU, LGALS3BP, ANGPTL2, CRYAB and ITGB8)." (PMID 25360666, 2014). "The results show that the expression of CDK4 and ANGPTL2 in glioma may be affected by CNV." (PMID 36358948, 2022). "We also observed an enrichment of the ANGPTL signaling pathway between glioma (mainly from Clusters C1) and TAM (Cluster C0), mediated by angiopoietin-like 2 (ANGPTL2) and toll-like receptor 4 (TLR4)." (PMID 38515213, 2024). "In addition, the knockdown of ANGPTL2 and MEX3A reduces the proliferative and invasive abilities of glioma cells." (PMID 36358948, 2022). "From the transcriptome data analysis results in the public database, it was found that CDK4, PBK, ANGPTL2, TMEM100, and MEX3A were significantly up-regulated in the glioma samples compared with the normal samples, whereas NEGR1 and SLC2A3 were down-regulated in the glioma samples at the mRNA level." (PMID 36358948, 2022).